ARPC5L (actin related protein 2/3 complex subunit 5 like)
Description:
May function as component of the Arp2/3 complex which is involved in regulation of actin polymerization and together with an activating nucleation-promoting factor (NPF) mediates the formation of branched actin networks.
Synonyms: ARC16-2; MGC3038; ARPC5B
Tractability: Small molecule: a structure with a bound ligand is known. PROTAC: ubiquitination databases record sites on it; its protein half-life has been measured.
Gene: Protein-coding gene on chromosome 9 (124,862,130 to 124,877,733, forward strand). Ensembl gene ENSG00000136950.
Subcellular location: Cytoplasm, cytoskeleton
Gene Ontology:
Molecular function: protein binding; protein-macromolecule adaptor activity
Biological process: Arp2/3 complex-mediated actin nucleation; cell migration; regulation of actin filament polymerization
Cellular component: Arp2/3 protein complex; extracellular exosome; focal adhesion; actin cytoskeleton; cortical cytoskeleton; cytoskeleton; glutamatergic synapse; synapse
Genetic constraint (gnomAD): Loss-of-function variants: 4 observed, 15.05 expected, observed/expected ratio (o/e) 0.27, 90% interval 0.13 to 0.61. The upper end of that interval is the gene's LOEUF score, 0.61, which puts it in group 2 of 6, group 1 being the genes least tolerant of losing a copy. Missense variants: 151 observed, 191.05 expected, observed/expected ratio (o/e) 0.79, 90% interval 0.69 to 0.9. Synonymous variants: 78 observed, 71.69 expected, observed/expected ratio (o/e) 1.09, 90% interval 0.9 to 1.31.
Homologues: Orthologues: chimpanzee ARPC5L (100% identical), macaque ARPC5L (100% identical), pig ARPC5L (99% identical), dog ARPC5L (99% identical), guinea pig ARPC5L (99% identical), rabbit ARPC5L (99% identical), mouse Arpc5l (97% identical), rat Arpc5l (95% identical), rat Arpc5l-ps1 (95% identical), zebrafish arpc5la (77% identical), tropical clawed frog arpc5l (76% identical), zebrafish arpc5lb (72% identical), and 3 more. Paralogues in human: ARPC5 (68% identical).
Diseases named in the same sentence as ARPC5L in open-access papers:
ARPC5L is named in the same sentence as 9 diseases in open-access papers, as found by Europe PMC text mining. Sharing a sentence is not in itself a finding about the gene and the disease. The quoted sentences say what the papers report.
melanoma (2 papers, 2016 to 2023). A malignant, usually aggressive tumor composed of atypical, neoplastic melanocytes. "To explore the role of the two ArpC5 isoforms in lamellipodia architecture and cell migration, we used a CRISPR-Cas9 knockout (KO) approach to generate B16-F1 mouse melanoma cells lacking either ArpC5 (referred to as C5KO), ArpC5L (C5LKO), or both isoforms (C5/C5LKO)." (PMID 36662867, 2023).
E. coli infection (1 paper, 2021). "The expression of six genes (KRT18, ARPC5L, ACTG1, ARPC2, EZR, and YWHAZ) related to pathogenic E. coli infection was simultaneously increased with TNFRSF11B overexpression via gene set enrichment analysis (GSEA)." (PMID 34938284, 2021). "In addition, only six genes (KRT18, ARPC5L, ACTG1, ARPC2, EZR, and YWHAZ) related to pathogenic E. coli infection were simultaneously increased in both GSEA studies; these genes are mostly involved in focal adhesion, as determined via GO analysis." (PMID 34938284, 2021).
epilepsy (1 paper, 2015). A brain disorder characterized by episodes of abnormally increased neuronal discharge resulting in transient episodes of sensory or motor neurological dysfunction, or psychic dysfunction. "Moreover other significant connections of community C—the communities A, H, and B—include several genes involved in epilepsy processes, like SXN25 and ARPC5L, markers of intractable epilepsy." (PMID 26011637, 2015).
Salmonella Infections (1 paper, 2018). Infections with bacteria of the genus SALMONELLA. "On the other hand, FOXO signaling (TNFSF10, PRKAB1, GADD45B, STK4, STAT3), Salmonella infection (ARPC2, ARPC5L, CCL3L3, CCL4) and lysosome (LAPTM4B, HGSNAT, CD164, ATP6V0A2) pathways were up-regulated, albeit weakly, in the HLA-DR- Teff subset." (PMID 30231065, 2018).
tumor (1 paper, 2021). "In addition, six genes, KRT18, ARPC5L, ACTG1, ARPC2, EZR, and YWHAZ, were simultaneously enriched in tumors and tumor tissues highly expressing TNFRSF11B, which may enhance pathogenic E. coli focal adhesion, actin filament binding, and cadherin binding, as demonstrated by GO functional analysis." (PMID 34938284, 2021).
ARPC5L also shares sentences with these, for which no sentence is quoted: cancer (3 papers); breast carcinoma (1); hepatocellular carcinoma (1); renal carcinoma (1).